HTT (huntingtin)
Diseases named in the same sentence as HTT in open-access papers (continued):
Sharing a sentence is not in itself a finding about the gene and the disease.
proteinopathies (12 papers, 2010 to 2025). "HD is characterized as a protein-misfolding disease, where the Htt protein—a protein called huntingtin produced by the HTT gene—causes disruptions in normal biological functions by interacting with other proteins." (PMID 35682615, 2022). "In many of the common proteopathies, disease proteins such as α-synuclein, mutant Huntingtin, and TDP43 are surrounded by NF caps in structures called aggresomes." (PMID 40059823, 2025). "In the mutant HTT allele a CAG triplet repeat is expanded resulting in an elongated polyglutamine region of the Huntingtin protein, which is primarily responsible for proteopathy in HD." (PMID 31784689, 2019). "We also tested another cellular stress condition, mutant Huntingtin induced proteopathy." (PMID 31784689, 2019). "A scFv targeting the N-terminal amino acids adjacent to the expanded polyglutamine of huntingtin protein was previously shown to successfully prevent protein aggregation, underscoring the broad potential of this intrabody strategy for control of neurodegenerative diseases due to proteinopathy." (PMID 29662239, 2018). "Markers of non-AD proteinopathies such as pTDP43-409, oligomeric alpha-synuclein, and huntingtin (HTT), were among those upregulated in MCI." (PMID 40318118, 2025). "The importance of ROS in protein misfolding disorders is not a new concept; indeed the cytotoxicity of elevated ROS generated by mutant huntingtin has been convincingly demonstrated by the laboratory of Rubinsztein." (PMID 20885783, 2010).
R6 (12 papers, 2007 to 2026). "In conclusion, the present study shows that the presence of mutant huntingtin causes increased expression levels of Rho/Rock kinase pathway genes in HD leukocytes, postmortem brain tissues, and in R6/2 HD mice." (PMID 25941073, 2016). "We used the R6/1 HD mouse model, which expresses exon 1 of human huntingtin (HTTex1) with approximately 115 glutamines." (PMID 40832276, 2025). "To study how mutant huntingtin is affecting the number of active neurons and their activity, we used primary culture of striatal or cortical neurons from wild-type (WT) or R6/1 mice (HD) at 15 days in vitro (DIV)." (PMID 32466798, 2020). "The R6/1 HD transgenic mice were generated by using a construct with ∼1000 bp of the human Huntingtin gene HTT promoter, the entire HTT exon-1, including ∼116 CAG repeats, and 262 bp of HTT intron-1." (PMID 23468640, 2013). "To identify in-vivo evidence of a metal N-terminal huntingtin interaction we determined if mutant huntingtin distribution co-localizes with increases in metal levels in brains of 12-week-old R6/2 HD mice." (PMID 17396163, 2007). "Augmenting cholesterol in brain improved electrophysiology readouts in R6/2 HD mice which expresses mutant Huntingtin exon 1 including normalizing both membrane capacitance and inhibitory postsynaptic current (IPSC) frequencies in striatal medium spiny neurons." (PMID 33815086, 2021). "To test the hypothesis that IL-6 deficiency would be protective against the effects of mutant huntingtin, we generated R6/2 HD model mice that lacked IL-6." (PMID 32448329, 2020).
prion disease (11 papers, 2013 to 2025). A transmissible disease that is caused by a protein that is able to induce abnormal folding of normal cellular proteins, leading to characteristic spongiform brain changes, which are associated with neuronal loss without an inflammatory response. "Among these, important proteins that are known to aggregate in some neurodegenerative diseases were mapped in the brain, such as huntingtin (aggregation in HD), amyloid-beta in AD, alpha-synuclein in PD, and prion protein in prion diseases." (PMID 36517484, 2022). "It not only binds with Aβ-oligomers and fibrils in AD, but also binds readily with other amyloid proteins, such as α-synuclein (α-syn) in PD, huntingtin (HTT) in HD, phosphorylated tau (p-tau) in tauopathies and AD, as well as with prion proteins in prion diseases." (PMID 29857538, 2018). "Thus, as with poly-Q expanded mutant huntingtin protein, autophagy might play a protective role in prion disease." (PMID 24454378, 2013).
tauopathy (11 papers, 2018 to 2026). Neurodegenerative disorders involving deposition of abnormal tau protein isoforms (tau proteins) in neurons and glial cells in the brain. "Mutant huntingtin (mHTT) is the main cause of HD and is associated with impaired mitochondrial dynamics, ubiquitin‐proteasome system and autophagy, as well as tauopathy." (PMID 32865873, 2020). "Of special interest are the microtubule defects caused by either unproper post-translational modifications of tubulin molecules which result in defective intracellular transportation or P-tau and other pathogenic proteins, like toxic forms of PrP and huntingtin, which in turn enhance tauopathy." (PMID 36352320, 2023). "Besides, in tauopathy models, O-GlcNAcylation shows a harmful function against the mutation of huntingtin toxicity in fly models as well as in cells." (PMID 31827688, 2019). "Presence and distribution pattern of polyglutamine inclusions in individuals with tauopathies and pathological expansions in the HTT gene." (PMID 38418081, 2024). "Proteins such as amyloid-β (Aβ, related to AD), α-synuclein (α-Syn, related to PD), huntingtin (Htt, related to HD), and tau (related to AD and other tauopathies) have emerged as potential culprits regarding neurodegeneration." (PMID 38393521, 2024). "To determine if mutant huntingtin aggregates correlated with tauopathy in the YAC128 NSC model, we measured the expression of phospho‐PHF‐tau (Ser202/Thr205) and total Tau (Tau5)." (PMID 32865873, 2020). "Next, we studied whether patients with tauopathies and pathological expansions of HTT had a differential distribution pattern based on the subtype of tauopathy." (PMID 38418081, 2024).
schizophrenia (10 papers, 2011 to 2025). A major psychotic disorder characterized by abnormalities in the perception or expression of reality. "The highest three scoring genes have all been previously shown to play important roles in the brain: ACTL6A, a chromatin remodeling factor which is required for the development of neural progenitors; VRK2, a gene implicated in schizophrenia; and the Huntington’s gene, HTT." (PMID 25970446, 2015). "Given the close interaction of HTT with the NMDA receptor mediated glutamate signaling system, its relationship to schizophrenia, though currently unclear, deserves future investigation." (PMID 23577129, 2013).
breast cancer (9 papers, 2013 to 2024). A primary or metastatic malignant neoplasm involving the breast. "In the same report, it has been shown that downregulation of HTT was also associated with poor survival of breast cancer patients." (PMID 28559546, 2017). "Wild-type huntingtin was shown to inhibit breast cancer metastasis by regulating expression and localization of tight junction protein ZO1." (PMID 37298337, 2023). "In mice models, mutant huntingtin was shown to accelerate breast cancer development and metastasis, reducing the endocytosis of the ErbB2/HER receptor kinase." (PMID 37298337, 2023). "The same study showed that downregulation of HTT mRNA and protein can be a biomarker for breast cancer metastasis." (PMID 37298337, 2023). "Downregulation of HTT transcription and protein levels is a key factor in poor prognosis and metastasis development of breast cancer." (PMID 33062007, 2020). "HTT expression is downregulated in breast cancer and regulates cancer cell differentiation via the maintenance of tight junctions." (PMID 33282738, 2020). "miR-146a has specificity to target the HTT gene, and HTT plays a vital role in oral and breast cancer biology and many other cellular activities." (PMID 33282738, 2020). "Recently, it was reported that the expression of HTT is low at both mRNA and protein level in case of metastatic breast carcinomas." (PMID 28559546, 2017). "We demonstrate that mutant huntingtin accelerates tumourigenesis in two mouse breast cancer models, increases epithelial–mesenchymal transition (EMT) of cancer cells and favours lung metastasis in mice." (PMID 23300147, 2013). "Thion and colleagues had reported the anti-metastatic role of the HTT gene in breast cancer." (PMID 33282738, 2020). "Here we propose that mutant huntingtin influences breast cancer progression." (PMID 23300147, 2013). "While research on HD has mostly focused on neurological symptoms, we investigated whether breast cancer could be influenced by the expression of mutant huntingtin." (PMID 23300147, 2013). "Here we investigated whether mutant huntingtin could influence the progression of breast cancer after we found the protein to be expressed in both normal mammary epithelia and tumours." (PMID 23300147, 2013). "Indeed, we show that mammary tumours appear earlier in mouse breast cancer models expressing mutant huntingtin as compared to control mice expressing wild-type huntingtin." (PMID 23300147, 2013). "In HD populations mammary tumors appear earlier and are more invasive and mutant Huntingtin increases cell motility supporting the notion that mutant Huntingtin affects adhesion and/or actin dynamics; furthermore, reduction of normal Huntingtin correlates with increased invasive carcinoma." (PMID 30768638, 2019). "We also found an inverse correlation between the length of the abnormal CAG expansion and the age of breast cancer onset, suggesting that the CAG length in huntingtin may be a prognostic factor." (PMID 23300147, 2013). "The presence of SP1 together with IL2 signaling regulators, IGFBP2, IMPDH2 and HTT in separate subnetworks that excludes RAC signaling component might indicate the presence of at least two non-redundant mechanisms in P-inter breast cancers that may determine patient outcomes." (PMID 26257336, 2015).
Dystonia (9 papers, 2018 to 2025). An abnormally increased muscular tone that causes fixed abnormal postures. "Aggregation of mutant Huntingtin protein was diminished, and motor deficits such as hindlimb clasping and dystonia and general locomotor activity were also improved." (PMID 32608035, 2020).
Genetic neurodegenerative disease (9 papers, 2013 to 2024). "HD is a genetic neurodegenerative disease caused by an expansion in the polyglutamine region in exon 1 of the Huntingtin (HTT) gene located on human chromosome 4." (PMID 39765675, 2024). "HD, a genetic neurodegenerative disease, is thought to be associated with abnormal modifications of huntingtin protein (HTT), which may play a critical role in the pathogenesis of HD." (PMID 38347638, 2024). "HD is a genetic neurodegenerative disease caused by the abnormal expansion of the CAG trinucleotide repeat in the huntingtin gene, which leads to a polyglutamine strand at the N-terminus of huntingtin protein." (PMID 37238624, 2023).
Lewy body dementia (9 papers, 2013 to 2024). A progressive form of dementia characterized by the presence of protein deposits called Lewy bodies in the midbrain and cerebral cortex, and loss of cholinergic and dopaminergic neurons. "Recent examples of postmortem human brain tissues of individuals with Lewy body dementia, as well as neurons expressing mutated huntingtin proteins, show that these aggregates are in fact a crowded medley of vesicular structures." (PMID 38149872, 2023).
spinocerebellar ataxia type 1 (9 papers, 2009 to 2025). Spinocerebellar ataxia type 1 (SCA1) is a subtype of type I autosomal dominant cerebellar ataxia (ADCA type I) characterized by dysarthria, writing difficulties, limb ataxia, and commonly nystagmus and saccadic abnormalities. "Spinocerebellar ataxia type 1 (SCA1) and HD are polyglutamine disorders caused by expansion of a CAG repeat within the coding regions of the Ataxin-1 and Huntingtin proteins, respectively." (PMID 32899411, 2020). "For example, polyQ-expanded Huntingtin and Ataxin-1 are observed in Huntington's disease and spinocerebellar ataxia type-1 (SCA-1), respectively." (PMID 19389260, 2009). "Like CAA interruptions in HTT, CAT interruptions of the ATXN1 CAG repeat in four spinocerebellar ataxia 1 subjects supported better tracking of age at onset with the uninterrupted CAG repeat size, but, because CAT specifies histidine, this was interpreted as an effect of polyglutamine length." (PMID 31398342, 2019).
Spinocerebellar ataxia type 3 (7 papers, 2017 to 2025). "Huntington’s disease (HD) and spinocerebellar ataxia type 3 (SCA3, also called Machado-Joseph disease) are caused by extensive polyglutamine (polyQ) expansion of the huntingtin or ataxin-3 protein." (PMID 37545006, 2023). "CAG repeat tracts, which may undergo pathogenic expansion in HD and spinocerebellar ataxia type 3 (SCA3), are located in exon 1 of the HTT gene and exon 10 of the ATXN3 gene." (PMID 40171277, 2025).
Atrophy (5 papers, 2011 to 2024). Any weakening or degeneration, especially through lack of use. "This disease is driven by striatal atrophy with some loss in cortical regions, stemming from trinucleotide expansion mutations to the HTT (huntingtin) gene." (PMID 39578912, 2024). "Furthermore, it has been observed that the increase in Huntingtin expression in leukocytes has been associated with the disease progression and atrophy of the caudate nucleus, suggesting a possible role as a biomarker of disease progression." (PMID 39768315, 2024).
mood disorder (5 papers, 2013 to 2022). A cognitive disorder a disturbance in which the person's mood is hypothesized to be the main underlying feature. "Thus, the pathogenic polyQ expansion in HTT could lead to mood disorders not only by the gain of a new toxic function but also by the perturbation of its normal function." (PMID 24795586, 2014).
myotonic dystrophy type 1 (5 papers, 2011 to 2024). Steinert disease, also known as myotonic dystrophy type 1, is a muscle disease characterized by myotonia and by multiorgan damage that combines various degrees of muscle weakness, arrhythmia and/or cardiac conduction disorders, cataract, endocrine damage, sleep disorders and baldness. "They include: myotonic dystrophy type 1 (DM1), caused by a CTG expansion in the DMPK1 gene, Huntingdon's disease (HD), caused by a CAG expansion in the huntingtin gene (HTT) and Friedreich's ataxia, caused by GAA expansion in frataxin (FXN)." (PMID 33099215, 2020).
viral infection (5 papers, 2017 to 2024). "This event occurs when microglial cells are exposed to a stimulus, such as the accumulation of aberrant and/or misfolded proteins, like amyloid-β (Aβ) and huntingtin (HTT) during ageing, or ROS, or even viral infections." (PMID 36979440, 2023).
amyloidosis (4 papers, 2013 to 2024). A disorder characterized by the localized or diffuse accumulation of amyloid protein in various anatomic sites. "However, neocortical and hippocampal HTT immunoreactivity in aged Tg2576 mice appeared to be additionally associated with amyloid plaque pathology." (PMID 31109380, 2019).
cardiomyopathy (4 papers, 2014 to 2021). A disease of the heart muscle or myocardium proper. "HTT is ubiquitously expressed and in recent years it has become apparent that HD patients experience a wide array of peripheral organ dysfunction including severe metabolic phenotype, weight loss, HD-related cardiomyopathy and skeletal muscle wasting." (PMID 25339908, 2014). "The huntingtin gene (HTT) and its product are ubiquitously expressed, hence, the cardiomyopathy could also be driven by defects caused by its mutated form (mHTT) in the cardiomyocytes themselves." (PMID 35004919, 2021). "Mutant huntingtin (mHTT) is ubiquitously expressed so the cardiomyopathy could be the result of deficits in the cardiomyocytes themselves and/or in the dysautonomia driven by the nervous system." (PMID 35004919, 2021). "HTT is expressed throughout the body and the mutant protein not only affects the brain but also peripheral tissues as weight loss, cardiomyopathies and skeletal muscle malfunction have been described for HD." (PMID 32295075, 2020). "In the R6/2 mouse, it has been suggested that the cardiomyopathy is caused by altered central autonomic pathways, since neither mutant huntingtin aggregates nor a HD-specific transcriptional dysregulation was identified in cardiac tissue, even at the end stage of disease." (PMID 27181166, 2016).
Obesity (4 papers, 2014 to 2025). Accumulation of substantial excess body fat. "In this regard, it is important to note that the obesity phenotype of BACHD mice was abolished when the expression of mutant Huntingtin was silenced in the hypothalamus." (PMID 25144554, 2014). "Interestingly, inactivating mutant huntingtin expression in the hypothalamus of BACHD mice completely resolved their obesity phenotype." (PMID 28273120, 2017). "Therefore, we speculated that obesity may impair hippocampal cognitive function by upregulating hippocampal HTT expression, whereas stigmasteride protects the hippocampus by downregulating HTT expression." (PMID 36998046, 2023).
oral cancer (4 papers, 2017 to 2025). "In oral cancer, miR-146a targets the HTT gene; in liver cancer, the FLAT mRNA; and in melanoma, SMAD4, regulating cell migration and invasion." (PMID 40277937, 2025). "Since miR-146a targets the HTT gene, we evaluated the expression pattern of the HTT gene in OSCC tissue and the role of the level of HTT expression on survival percentage and duration in oral cancer patients." (PMID 33282738, 2020). "HTT gene expression is downregulated in oral cancer tissues and is one of the candidate genes involved in oral cancer biology." (PMID 33282738, 2020). "In the present study, the inhibitory role of the alpha mangostin on the genes implicated in Oral cancer namely CALM3, ARRB1, HTT, and FLNAwas investigated through molecular docking techniques." (PMID 33214751, 2020). "Background and Aim: The genes ARRB1, FLNA, CALM3, and HTT are commonly expressed in oral cancer and have been hypothesized to be involved in the carcinogenic pathway." (PMID 33214751, 2020).
Rett syndrome (4 papers, 2015 to 2022). A severe neurodevelopmental disorder affecting the central nervous system. "The patient presented with a rare Rett-like syndrome and revealed two putative compound heterozygous LoF mutations in the HTT gene, which were inherited from both parents." (PMID 36293294, 2022).
bipolar disorder (3 papers, 2021 to 2023). A disorder of the brain that causes unusual shifts in mood, energy, activity levels and the ability to carry out day-to-day tasks. "The findings of the present brief report are intended to be proof of concept that justify further investigation into the role played by the IA of the HTT gene in the onset of bipolar disorder." (PMID 37761821, 2023). "The study of the HTT gene in a cohort of 69 patients with bipolar disorder did not identify any subjects in a pre-motor stage of HD; in fact, no patient was a carrier of the pathological allele." (PMID 37761821, 2023). "In the present study, we analyzed the HTT gene in a psychiatric cohort of patients affected by bipolar disorder in order to identify pre-motor HD patients and evaluate whether the length of CAG repeats may influence or contribute to the development of bipolar disorder." (PMID 37761821, 2023).
diabetes (3 papers, 2012 to 2020). "Since HTT is a scaffolding protein that connects cytoskeleton proteins to proteins of the endocytosis and exocytosis pathways, it is possible that mutant mHTT affects diabetes phenotypes related to these pathways." (PMID 31450785, 2019). "A further investigation of sortilins, tetraspanins and HLA/MHC genes, may lead to the understanding of the involvement of HTT and mHTT in the release of cellular vesicles, including exosomes, and how this might affect immunological pathways in diseases such as HD, diabetes and cancer." (PMID 31450785, 2019).